CASP4 (caspase 4)
Diseases named in the same sentence as CASP4 in open-access papers (continued):
Sharing a sentence is not in itself a finding about the gene and the disease.
tumor (80 papers, 2013 to 2026). "To further explore the role of CASP4 in regulating tumor immunotherapy, we investigated the association between the expression of CASP4 and immunomodulators such as immune checkpoint molecules, chemokines, and chemokine receptors using GEPIA2." (PMID 39075190, 2024). "CASP4 has previously been implicated in tumor genesis and progression, which has a variety of biological roles." (PMID 36552744, 2022). "In support, adenocarcinoma patients who had tumor-associated levels of caspase-4 higher than 377 pg/ml (n = 42/53, 79,3%) survived less (median = 0.925 years) than patients with lower levels (n = 11/53, 20,7%; median survival =3.03 years)." (PMID 33187551, 2020). "In this latter case, we stratified patients who presented EGFR mutation or MET, ROS1 or ALK translocation, herein defined as mutated (Mut+), and compared them to the levels of tumor-associated caspase-4." (PMID 33187551, 2020). "Taken together these data suggest that tumor tissues are characterized by high levels of caspase-4 and IL-1α which are associated to lower survival rate of NSCLC patients." (PMID 33187551, 2020). "In conclusion, we found that caspase-4 tumor tissues were associated with higher consumption of glucose in favor of fatty acid biosynthesis." (PMID 33014287, 2020). "Higher tumor-associated caspase-4 (n = 15, 88.2%) was associated to lower survival rate (median = 0.86 years) than those who had lower levels (n = 2, 11.8%; median = undefined)." (PMID 33187551, 2020). "We found that 35 patients out of 74 (red bar on the left), representing 47.3% of our database, were positive to tissue LDH and tumor-associated caspase-4." (PMID 33014287, 2020). "A great limitation to this study is the absence of follow-up information about COPD and healthy smokers, in order to better understand and associate the levels of the circulating caspase-4 to the establishment of a tumor mass, avoiding late diagnosis." (PMID 29721208, 2018). "More importantly, higher levels (cut-off value = 0.307 ng/ml) of caspase-4 in the tumor mass were associated to reduced overall survival (median 0.92 years) compared to NSCLC patients with lower levels (median 3.02 years)." (PMID 29721208, 2018). "In order to evaluate the tissue levels of the caspase-4 (defined as tumor-associated caspase-4), we used the ELISA kit developed by ImmunePharma S.r.l." (PMID 29721208, 2018). "Taken altogether, these data imply that the circulating, tumor-associated caspase-4 represents a novel selective diagnostic and prognostic biomarker." (PMID 29721208, 2018). "According to the Log-rank Mantel-Cox and Gehan-Breslow-Wilcoxon test, the survival rate of NSCLC patients who had higher expression of tumor-associated caspase-4 was significantly lower (p < 0.0001) than those who had lower levels." (PMID 29721208, 2018). "In this study we found that the circulating/tumor-associated caspase-4 is a novel diagnostic, predictive and prognostic biomarker for non-small cell lung cancer (NSCLC) patients." (PMID 29721208, 2018). "Furthermore, an association between CASP4 levels and outcomes after tumor treatment has been identified." (PMID 39075190, 2024). "A previous study has identified tumor-associated CASP4 as a new diagnosis, prediction and prognosis biomarker for NSCLC patients, nevertheless, the relation of the CASP4-mediated pyroptosis with LUSC development is still unknown." (PMID 35153782, 2022). "Moreover, stage III NSCLC patients had worse survival rate (median = 0.65 years) when tumor-associated caspase-4 was > 377 pg/ml compared to patients who had lower levels (median = not revealed; n = 2)." (PMID 33187551, 2020). "However, patients with higher levels of tumor-associated caspase-4 but positive for PD-L1 (black line) showed lower survival rate (p = 0.033) than patients with low caspase-4 but positive for PD-L1 (green line, n = 1/75, 1.3%, median survival = undefined)." (PMID 33187551, 2020).
tumor (continued). "Interestingly, the cleaved form of caspase-4, herein identified as tumor-associated caspase-4, statistically increased from stage I up to stage III (stage I to III)." (PMID 33187551, 2020). "Therefore, tumor-associated as well as circulating caspase-4 suggest that the inflammatory pattern in tumor cells alters the metabolomic profile to favor cell proliferation rather than cell death, as we recently demonstrated." (PMID 33187551, 2020). "Similarly, NSCLC patients at stage II had lower median survival rate when tumor-associated caspase-4 levels were higher than 377 pg/ml." (PMID 33187551, 2020). "Moreover, in order to understand the prognostic value of the tumor-associated caspase-4, we analyzed the overall survival rate of NSCLC patients." (PMID 29721208, 2018). "In addition, tumor-associated caspase-4 has a prognostic value, opening new therapeutic perspectives for NSCLC patients." (PMID 29721208, 2018). "In conclusion, in this study we propose the circulating and tumor-associated caspase-4 as a diagnostic biomarker for NSCLC that can be detected in both blood (in a non-invasive manner) and tissues with high sensitivity/true positive values compared to what so far described in the literature." (PMID 29721208, 2018). "The presented results are consistent with our experimental data, and we also noted a decrease in the mean level of expression of the CASP4 gene in the tumor tissue of TNBC patients compared to the control tissue." (PMID 40806590, 2025). "Building on our previous work, we confirm, in independent patient cohorts, that caspase-4 is selectively expressed in the epithelial compartment of CRC tumor tissue compared to adjacent normal tissue." (PMID 39866724, 2025). "Non–cell death functions of caspase-4 including cell division (via modulation of actin dynamics) and tumor angiogenesis (via Notch1 signaling regulation), have also been identified." (PMID 39866724, 2025). "IHC staining of patient colonic tissue (Irish CRC cohort, Table A1), revealed that caspase-4 levels were significantly increased in the epithelium of tumor compared to adjacent normal tissue." (PMID 39866724, 2025). "Further, CASP4 knockout attenuates tumor angiogenesis and metastasis in subcutaneous tumor mouse models." (PMID 38849594, 2024). "The caspase (aspartate-specific cysteine protease) family contains at least 12 members (including CASP1, CASP3, and CASP4) that have a significant impact on cell death, inflammatory responses, the immune microenvironment, and tumor suppression." (PMID 39075190, 2024). "To explore the correlation between CASP4 expression and the proportions of infiltrating immune cells, we assessed the status of 22 tumor-infiltrating immune cell types using CIBERSORT analysis." (PMID 39075190, 2024). "CASP4, as a gene related to cell apoptosis, is differentially expressed in a variety of tumors, and can be used to predict the prognosis of tumor patients." (PMID 37006234, 2023). "Recently, it has been found that intracellular LPS can activate the Caspase-4/5/11 pathway, induce pyroptosis, and inhibit tumour growth." (PMID 36702978, 2023). "For example, GBP2 activated caspase-4, that triggered cell death and inhibited tumor cell proliferation, and SLC40A1, that acted as a negative regulator of ferroptosis." (PMID 36899891, 2023). "Subsequently, we applied the COX regression model and conducted ROC analysis to identify the final set of tumor-related genes (TRGs), which included CASP4, FYN, TOB1, and CLEC2B." (PMID 37753069, 2023). "CASP4 expression was directly correlated with tumor grade, and the higher the tumor grade, the higher the expression of CASP4." (PMID 36713560, 2022). "GSDMB is also involved in pyroptosis, it can promote atypical pyroptosis by enhancing the activity of caspase-4 and has the function of inhibiting the proliferation of tumor cells." (PMID 35571063, 2022).
tumor (continued). "B cells, T cells, NK cells, and macrophages as well as other TIIC levels in high-CASP4-expression patients increased, indicating that it can modulate tumor genesis and development by changing the TME." (PMID 36552744, 2022). "The analysis of the clinical and gene expression data of 689 primary tumors from TCGA, 984 primary tumors from CGGA, and 1,157 normal tissues from GTEx showed that CASP4 expression was higher in tumor tissues than in normal tissues." (PMID 36713560, 2022). "In especial, CASP4 can promote tumor progression by promoting the synthesis and accumulation of fatty acids, while NLRP1 acts on RAS/ERK signaling pathway." (PMID 35633405, 2022). "This indicated that CASP4 plays an important role in infiltrating immune cells to affect the composition of the tumor immune microenvironment." (PMID 36713560, 2022). "The pathway analysis results showed that normal tissue Treg and non-tumor diseased tissue Treg shared 15 upregulated caspase-4 secretomic pathways." (PMID 34084175, 2021). "The fold changes of caspase-4 from tumor to normal and from metastasis to the tumor were about 0.76 and 1.41, respectively." (PMID 34659633, 2021). "Treg from non-tumor diseased tissues and tumors shared four upregulated caspase-4 secretomic pathways." (PMID 34084175, 2021). "Herein, we investigated the expression of CASP4 in tumor tissues and its relationship with clinical prognosis, immune infiltration, and drug sensitivity status of ccRCC patients." (PMID 33584797, 2020). "We moved on by evaluating the levels of these metabolites according to the levels of caspase-4 in the tumor mass based on a previous identified cut-off (0.307 ng/ml)." (PMID 33014287, 2020). "Previous studies have reported the relationship between the expression of CASP4 and the clinicopathological parameters of tumor patients." (PMID 33584797, 2020). "In support to our previous data on the lipidomic profile, higher levels of fatty acid-binding protein were found in caspase-4-positive tumor tissues." (PMID 33014287, 2020). "In this study, we found that the TCA cycle was supported by higher expression of SDHA in caspase-4 positive tumor tissues." (PMID 33014287, 2020). "Herein, the expression of CASP4 in tumor tissues and its relationship with the clinical prognosis of ccRCC patients was investigated." (PMID 33584797, 2020). "Caspase-4 positive tumor tissues had significantly higher levels of transaldolase and pyruvate kinase." (PMID 33014287, 2020). "Nonetheless, in support, other fatty acids (i.e., stearic, linoleic and arachidonic acids) evaluated in this study were reduced in caspase-4 positive tumor tissues." (PMID 33014287, 2020). "The in vivo studies in mice show the contribution of CASP4 to tissue invasion and tumor development." (PMID 30531914, 2018). "In contrast, NSCLC patients who had lower levels of caspase-4 (<0.377 ng/ml) in the tumor mass had longer median survival (3.02 years), which was three-fold higher compared to patients who had higher levels of caspase-4 (0.92 years)." (PMID 29721208, 2018). "In order to investigate the effect of CASP4-silencing on tumor invasion and growth, xenograft experiments in athymic nude mice were performed." (PMID 30531914, 2018). "Higher levels of circulating CASP4 was detected in NSCLC patients than in healthy subjects, and higher levels of CASP4 in the tumor mass were associated to reduced overall survival compared to NSCLC patients with lower levels." (PMID 30531914, 2018). "Tissue levels of caspase-4 in the tumor mass showed that 72 (72.7%) out of 99 patients were positive." (PMID 29721208, 2018). "Finally, GSEA confirmed the involvement CASP4 upregulation in pathways related to tumor cellular pyroptosis and immunity." (PMID 39075190, 2024). "However, in epithelial tumors and pancreatic cancer, CASP4 has been shown to play an integral role in promoting tumor cell migration, cell–matrix adhesion and tissue invasion." (PMID 39075190, 2024).
tumor (continued). "To ascertain whether CASP4 influences immunotherapy by affecting tumor-infiltrating immune cells, we analyzed the potential association between CASP4 expression and tumor-infiltrating immune cells in multiple cancer types based on the TIMER database." (PMID 39075190, 2024). "In addition, we employed the TIP database to analyze the relationship between CASP4 and different aspects of tumor immunotherapy processes." (PMID 39075190, 2024). "CASP4, CASP6, CASP8, IL18, and PYCARD were associated with clinical stage, which means that IL18 and PYCARD may be involved in tumor progression." (PMID 36882663, 2023). "Finally, we observed that caspase-4 induction occurs in vivo in mouse models of tumor suppression and ageing." (PMID 34916628, 2022). "Thus, our data indicates that caspase-4 functions in the arrest in cell proliferation is independent of its downstream effect on IL-1β activation, suggesting a split in tumor suppressive and proinflammatory functions." (PMID 34916628, 2022). "More evidence is required to reveal the function of CASP4 in pyroptosis and tumor promotion." (PMID 34820372, 2021). "Furthermore, we used the NCI-60 database to explore the relationship between CASP4 expression and drug resistance in tumor cells." (PMID 33584797, 2020). "Notably, the function of CASP4 in autophagy and its effect on the growth and migration of tumor cells indicate that it is a potential target for cancer therapy." (PMID 33584797, 2020). "In conclusion, we found that the recently identified caspase-4 positive subpopulation of NSCLC patients is characterized by a lipidomic profile accompanied by alternative pathways to guarantee glucose metabolism in favour of tumor cell proliferation." (PMID 33014287, 2020). "Interestingly it has been recently developed a sensitive and specific test to quantify CASP4 in plasma and tumor mass." (PMID 30531914, 2018). "Importantly because external stimuli (Ca2+ and EGF) can modulate the effects of CASP4, the microenvironment can influences CASP4-mediated cellular events including tumor development." (PMID 30531914, 2018). "Interestingly, the expression of the CASP4 pseudogene is lower in tumor samples than normal, which is the expression profile expected for a ceRNA that promotes CASP4 expression." (PMID 25765044, 2015). "Since many of the mechanisms responsible for the multifactorial functions of MIF have still to be identified, we have provided important new information with regard to the role of MIF in regulating tumor cell proliferation and programmed cell death by caspase-3 and caspase-4 dependent pathways." (PMID 23522304, 2013). "CASP4 expression may serve as an independent prognostic marker, as it correlates with a variety of clinical features, particularly the pathological stage and status of the tumor." (PMID 39075190, 2024). "Therefore, we stratified NSCLC patients as PD-L1 positive vs PD-L1 negative according to the levels of tumor-associated caspase-4." (PMID 33187551, 2020). "Lung tumor-associated caspase-4 was related to tumor cell proliferation, rather than cell death." (PMID 33187551, 2020). "Similarly, in our experimental conditions, we found that all patients positive for tumor-associated caspase-4 had high levels of LDH, which was not a measure of cell death as reported in in vitro assays, but of cancer progression." (PMID 33187551, 2020). "Differential expression analysis revealed that CASP4, CHMP4B, ELANE, IL-1A, and TNF were significantly upregulated in tumor samples (p < 0.05)." (PMID 40538398, 2025).
tumor (continued). "Regarding caspases, tumor cells exhibited predominantly high expression of CASP4, and immune cells showed high expression of CASP1, CASP4, and CASP8, while CASP5 plays an important role in stromal cells." (PMID 38229080, 2024). "Lymph node metastasis had significant difference with the CASP4 and GSDMD expression (P < 0.05); tumor volume had significant difference with CASP1 and CASP5 expression (P < 0.05)." (PMID 37194012, 2023). "According to our analytical results, CASP4, CASP5, and CASP9 were upregulated in the tumor tissues, and their high expression indicated poor survival rate." (PMID 35153782, 2022). "Tumor tissues showed obviously higher expression levels of NLRP1, IL18, TNF, and CASP4 than did the normal tissues." (PMID 35785176, 2022). "QRT-PCR showed that the expression of AIM2, CASP4, GSDMB, NOD2, and RBCK1 was significantly upregulated in tumor samples." (PMID 36248876, 2022). "In the 27 PRGs, apart from CASP4, CHMP6, CHMP7, GSDMD, and TP63, the other 22 PRGs were expressed differentially at a significant level between primary tumor and paracancerous samples." (PMID 35938142, 2022). "Immunohistochemistry indicated that CASP4 was expressed at high levels in tumor tissues but weakly expressed in adjacent normal tissues, and the difference in NLRP1 expression between tumor and adjacent normal tissues was opposite to that of CASP4." (PMID 35633405, 2022). "IHC staining validated that the protein levels of AIM2, CASP4, GSDMB, NOD2, and RBCK1 in tumor tissues were much higher than that in adjacent normal tissues." (PMID 36248876, 2022). "Then, we investigated the expression levels of AIM2, CASP4, GSDMB, NOD2, and RBCK1 in cell lines and tumor tissues by qRT-PCR, IHC." (PMID 36248876, 2022). "As previously observed in mRNA expression level, CASP4, GPX4, IL18, NLRP1, and IRF1 were upregulated in tumor samples, whereas PLCG1 was downregulated." (PMID 35000541, 2022). "In summary, three genes in the PRG model (CASP1, CHMP6, and GZMA) is shown to be a protective factor, while the other three genes (CASP4, DHX9, and DFNA5) were defined as tumor-promoting factors." (PMID 34820372, 2021). "TNM plot analysis showed that the expression of caspase-4 and GSDME was significantly inhibited in clinical tissues in normal, tumor (1097), and metastatic states, which was consistent with the earlier investigation." (PMID 34659633, 2021). "Based on the verification of the tissues from COAD patients by the method of qPCR, the results showed that CASP4, CASP5, PRKACA, and NOD1 were expressed differentially between normal and tumor tissues." (PMID 34938319, 2021). "Based on the hazard ratio (HR), the downregulated PLCG1, CASP6, CASP4, and AIM2 were considered tumor suppressors, whereas the upregulated PRKACA, NLRP9, and BAK1 were regarded as oncogenes." (PMID 34805183, 2021). "Cleaved-caspase 4, 7, 12 showed a significant increase in group C (tumor-bearing + FLX) and group G (tumor-bearing + CUMS + FLX) compared with group B (tumor-bearing control) and group F (tumor-bearing + CUMS), respectively." (PMID 34413774, 2021). "Because LDH is a key enzyme in the conversion of the pyruvate to lactate under anaerobic conditions and links to tumor progression and prognosis, we went on by evaluating tissue-derived LDH and correlated it to the levels of tissue caspase-4." (PMID 33014287, 2020). "Finally, we found that the abnormal expression of CASP4 may be related to tumor drug resistance." (PMID 33584797, 2020).